MYCBP2 (MYC binding protein 2)
Description:
Atypical E3 ubiquitin-protein ligase which specifically mediates ubiquitination of threonine and serine residues on target proteins, instead of ubiquitinating lysine residues. Shows esterification activity towards both threonine and serine, with a preference for threonine, and acts via two essential catalytic cysteine residues that relay ubiquitin to its substrate via thioester intermediates. Interacts with the E2 enzymes UBE2D1, UBE2D3, UBE2E1 and UBE2L3. Plays a key role in neural development, probably by mediating ubiquitination of threonine residues on target proteins (Probable). Involved in different processes such as regulation of neurite outgrowth, synaptic growth, synaptogenesis and axon degeneration (By similarity). Required for the formation of major central nervous system axon tracts (By similarity). Required for proper axon growth by regulating axon navigation and axon branching: acts by regulating the subcellular location and stability of MAP3K12/DLK (By similarity). Required for proper localization of retinogeniculate projections but not for eye-specific segregation (By similarity). Regulates axon guidance in the olfactory system (By similarity). Involved in Wallerian axon degeneration, an evolutionarily conserved process that drives the loss of damaged axons: acts by promoting destabilization of NMNAT2, probably via ubiquitination of NMNAT2 (By similarity). Catalyzes ubiquitination of threonine and/or serine residues on NMNAT2, consequences of threonine and/or serine ubiquitination are however unknown. Regulates the internalization of TRPV1 in peripheral sensory neurons (By similarity). Mediates ubiquitination and subsequent proteasomal degradation of TSC2/tuberin. Independently of the E3 ubiquitin-protein ligase activity, also acts as a guanosine exchange factor (GEF) for RAN in neurons of dorsal root ganglia. May function as a facilitator or regulator of transcriptional activation by MYC. Acts in concert with HUWE1 to regulate the circadian clock gene expression by promoting the lithium-induced ubiquitination and degradation of NR1D1.
Synonyms: KIAA0916; PAM; FLJ10106; PHR1; Myc-bp2; Phr
Tractability: Small molecule: a structure with a bound ligand is known. Antibody: its Gene Ontology location is reachable by antibodies, with medium confidence. PROTAC: UniProt records ubiquitination sites on it; ubiquitination databases record sites on it; its protein half-life has been measured.
Target class: Enzyme; Transferase
Gene: Protein-coding gene on chromosome 13 (77,042,474 to 77,327,094, reverse strand). Ensembl gene ENSG00000005810.
Subcellular location: Nucleus; Cell projection, axon; Cytoplasm, cytoskeleton
Subcellular location (Human Protein Atlas): Nucleoplasm; Cytosol; Vesicles
Gene Ontology:
Molecular function: guanyl-nucleotide exchange factor activity; protein binding; small GTPase binding; ubiquitin protein ligase activity; zinc ion binding; identical protein binding
Biological process: circadian regulation of gene expression; positive regulation of protein ubiquitination; protein K48-linked ubiquitination; protein ubiquitination; axon guidance; central nervous system projection neuron axonogenesis; neuromuscular process; proteasome-mediated ubiquitin-dependent protein catabolic process; regulation of axon guidance; regulation of synaptic assembly at neuromuscular junction; synaptic assembly at neuromuscular junction
Cellular component: membrane; nucleoplasm; nucleus; cytoplasm; plasma membrane; ubiquitin ligase complex; axon; cytoskeleton; microtubule cytoskeleton
Genetic constraint (gnomAD): Loss-of-function variants: 88 observed, 431.5 expected, observed/expected ratio (o/e) 0.2, 90% interval 0.17 to 0.24. The upper end of that interval is the gene's LOEUF score, 0.24, which puts it in group 1 of 6, group 1 being the genes least tolerant of losing a copy. Missense variants: 3,784 observed, 5,314.6 expected, observed/expected ratio (o/e) 0.71, 90% interval 0.69 to 0.73. Synonymous variants: 1,751 observed, 1,853.6 expected, observed/expected ratio (o/e) 0.94, 90% interval 0.91 to 0.98.
Homologues: Orthologues: chimpanzee MYCBP2 (99% identical), dog MYCBP2 (99% identical), pig MYCBP2 (98% identical), macaque MYCBP2 (97% identical), mouse Mycbp2 (97% identical), rat Mycbp2 (97% identical), guinea pig MYCBP2 (95% identical), tropical clawed frog mycbp2 (88% identical), zebrafish mycbp2 (84% identical). Paralogues in human: FBXO24 (3% identical).